INS (insulin)
Diseases named in the same sentence as INS in open-access papers (continued):
Sharing a sentence is not in itself a finding about the gene and the disease.
diabetes (continued). "Diabetes mellitus (DM) is a chronic metabolic disease caused by insufficient insulin secretion or deficiencies in insulin action or both, mainly characterized by hyperglycemia." (PMID 38167509, 2024). "In multiple human populations, CDKAL1 variants are associated with risk for type 2 diabetes mellitus and decreased insulin secretion." (PMID 38092373, 2024). "Diabetes mellitus (DM), a chronic metabolic disorder, is marked by either an absolute or relative deficiency in insulin, prolonged hyperglycaemia and insulin resistance." (PMID 38774996, 2024). "Diabetes is one of the most common metabolic disorders, which is mainly caused by insulin hyposecretion or insulin resistance and characterized by high blood glucose level." (PMID 39434840, 2024). "This underscores the potential of CPCM as a therapeutic strategy for improving metabolic health, as elevated SCFAs are linked to better insulin sensitivity and glucose management—critical factors in diabetes management and complication prevention." (PMID 39840100, 2024). "Outcomes included blood pressure, a composite cardiovascular disease indicator, and specific cardiovascular disease risk factors such as diabetes mellitus (type I), insulin resistance, waste circumference, and triglyceride levels." (PMID 38704541, 2024). "Treatment with analogue insulin was associated with a reduction in diabetes-related complications compared to human insulin, but the benefits and cost savings did not offset the increased costs." (PMID 38694591, 2024). "In humans, lower Klotho levels are associated with increased fasting glucose, insulin resistance, increased glycated hemoglobin, and diabetes prevalence." (PMID 38501099, 2024). "In our earlier studies, we found that the serum biomarker cathepsin S was associated with the risk of developing diabetes, probably by impairing insulin sensitivity." (PMID 38731158, 2024). "A previous study suggested an association between diabetes-related distress and insulin therapy and total sleep time." (PMID 38669401, 2024). "Diabetes mellitus (DM) is a metabolic disorder characterized by hyperglycemia, primarily caused by insufficient insulin secretion (type 1 diabetes, T1DM) or insulin resistance (type 2 diabetes, T2DM)." (PMID 39564114, 2024). "Recent studies have linked the role of some miRNAs and lncRNAs with diabetes pathogenesis in cell functions associated with insulin function, β-cell activity, and glucose metabolism." (PMID 38326874, 2024). "Compared with all other diabetes medications, insulin had the highest rate of serious medical outcomes associated with therapeutic errors starting in 2002." (PMID 39300573, 2024). "A balanced gut microbiota, or eubiosis, is associated with improved glucose metabolism and insulin sensitivity, potentially reducing the risk of diabetes-related complications." (PMID 39458444, 2024). "Diabetes mellitus is a chronic metabolic condition marked by high blood glucose levels caused by inadequate insulin synthesis or poor insulin use." (PMID 38667785, 2024). "It has been proven that, diabetes in the course of CP is accompanied by concomitant insulin, glucagon, and pancreatic polypeptide (PP) deficiency." (PMID 39596226, 2024). "Diabetes mellitus is a multi-etiological metabolic disease caused by insufficient insulin secretion and/or defective function, which is also a major cause of vascular calcification." (PMID 38405155, 2024). "Some studies even reported it as the leading risk factor for sarcopenia in diabetes, independently of diabetes type or insulin treatment." (PMID 38398421, 2024). "Diabetes is characterised by chronic hyperglycaemia that is caused by defects in either insulin secretion, insulin action, or both." (PMID 39201727, 2024). "Diabetes mellitus is a chronic metabolic disorder characterized by elevated blood glucose levels caused by deficiencies in insulin production, insulin activity, or both." (PMID 38885218, 2024).
diabetes (continued). "This modulation represents a key mechanism through which SQ exerts its hypoglycemic, insulin sensitivity-enhancing, and anti-inflammatory effects, exhibiting its multifaceted approach to combating diabetes and associated metabolic disturbances." (PMID 38708085, 2024). "Patients with the MODY1 form of diabetes have a loss of glucose priming effect, expressed as mild hyperglycemia on insulin secretion." (PMID 39902162, 2024). "CP's underlying pathophysiology of diabetes is mostly dependent on the disrupted insulin secreting capacity of the pancreatic islets." (PMID 39424751, 2024). "This is also true even when the therapy’s ambitions are limited to improving the patient’s quality of life by diminishing exogenous insulin doses or alleviating the risk of severe hypoglycemia as seen in difficult-to-manage brittle diabetes." (PMID 39744044, 2024). "Diabetes is a metabolic disorder caused by insufficient insulin secretion or impaired insulin action in the body." (PMID 39707185, 2024). "Additional studies in adolescents are needed to assess the reproducibility of insulin sensitivity and secretion indices, as these indices are important for informing clinical and epidemiological research studies evaluating future diabetes risk." (PMID 39726936, 2024). "The progression of diabetes is intricately linked to islet cell damage, with these cells playing a pivotal role in insulin production and glucose regulation." (PMID 39684868, 2024). "Diabetes mellitus (DM) is a systemic metabolic condition that causes hyperglycemia and microvascular consequences as a result of impaired insulin and faulty insulin secretion." (PMID 38256586, 2024). "Skeletal muscle regulates more than 75% of insulin-mediated glucose disposal, which helps control glucose and lipids while reducing the risk of diabetes." (PMID 39768974, 2024). "In the case of the K+ and Ca2+ action for the insulin secretion process, its decreased intake has an impact on reduced risk of diabetics." (PMID 38612580, 2024). "According to these authors, a longer duration of diabetes is generally associated with reduced insulin secretion capacity, which can lead to a reduction in BMI." (PMID 38710948, 2024). "Among the top 20 pathways, pancreatic secretion, calcium signaling pathway, type 2 diabetes mellitus, and insulin secretion are the significantly enriched pathway associated with in diabetes progression." (PMID 38557554, 2024). "Type 1 diabetes mellitus (T1DM) is a metabolic disorder characterized by an absolute deficiency of insulin due to pancreatic failure." (PMID 38903770, 2024). "Diabetes mellitus (DM) is a chronic metabolic disorder characterized by hyperglycemia, which can be caused by reduced insulin action, inadequate insulin synthesis, or both." (PMID 38399476, 2024). "Vaspin gene expression has been shown to decrease with loss of body weight and progression of diabetes, and vaspin serum levels return to normal with insulin and pioglitazone treatment." (PMID 39051061, 2024). "Diabetes mellitus (DM) is defined as a group of diseases characterized by hyperglycemia, which is caused by either a decreased secretion of insulin (mainly type 1 of DM) or an impaired response of cells to this hormone (mainly type 2 of DM)." (PMID 39202319, 2024). "In patients with Type 1 Diabetes Mellitus, there exists an absolute deficiency of insulin in the portal vein." (PMID 39578883, 2024). "These pens can be extremely useful for older people who have mild memory impairment but who are otherwise capable of self-managing their diabetes (e.g. for reducing risk of hypoglycaemia and improving insulin treatment adherence)." (PMID 39138689, 2024). "The American Diabetes Association and the European Association for the Study of Diabetes treatment guidelines advise up to three NADs plus insulin until HbA1c control." (PMID 38392925, 2024).
diabetes (continued). "Impairment in insulin secretion from pancreatic beta cells, insulin deficiency due to beta-cell destruction, or insulin resistance within the target tissue can cause diabetes." (PMID 39063270, 2024). "As the insulin-producing beta-cells are the main producer of insulin in the body, their loss or dysfunction leads to persistent hyperglycemia and diabetes." (PMID 38825059, 2024). "Type 1 diabetes mellitus (T1DM) is a chronic metabolic disease characterized by the loss of endogenous insulin production resulting from autoimmune-mediated pancreatic beta cell destruction." (PMID 38435452, 2024). "The regulation of diet, obesity, and inflammation in type 2 diabetes is believed to play a crucial role in enhancing insulin sensitivity and reducing the risk of onset diabetes." (PMID 39606781, 2024). "Although the precise mechanisms causing diabetes-related cognitive impairment are complicated, it is believed that aberrant insulin action and poor glucose metabolism play key roles." (PMID 39822457, 2024). "It is noteworthy to mention that our data is the first to report an increase in plasma insulin levels following NGR1 administration in an insulin-deficient animal model of diabetes." (PMID 39399466, 2024). "This bypasses the rest of the stomach and duodenum, reducing food absorption while decreasing appetite and increasing insulin sensitivity, leading to weight loss and better diabetes control." (PMID 38892885, 2024). "Peptide-based therapies in DM have expanded significantly beyond insulin, offering various mechanisms to improve glucose regulation, promote weight loss, and reduce the risk of complications in diabetes management." (PMID 39766270, 2024). "Diabetes mellitus (DM) is a chronic condition characterized by either partial or complete deficiency in insulin production or by resistance to its effects." (PMID 39200907, 2024). "For patients with ketoacidosis, it is suggested to correct water loss, restore blood volume by rehydration, and adjust blood glucose by continuously pumping low-dose insulin intravenously." (PMID 38577606, 2024). "Most classically, deficiency of insulin from the pancreas results in diabetes, leading to persistently elevated blood glucose levels due to impaired glucose uptake in peripheral tissues, particularly in muscle and adipose tissues." (PMID 38425548, 2024). "IL-1β is a pivotal inflammatory mediator implicated in diabetes mellitus and depression, associated with compromised insulin secretion and various depressive symptom mechanisms." (PMID 38916735, 2024). "This loss reverses crucial pathophysiological processes in diabetes, such as enhancing peripheral insulin sensitivity, improving cellular insulin signal transduction, boosting insulin secretion, and decreasing hepatic glucose production." (PMID 38362272, 2024). "Diabetes mellitus (DM) is a type of metabolic disease caused by insulin dysfunction resulting from absolutely or relatively insufficient insulin secretion." (PMID 39103956, 2024). "Type 1 diabetes mellitus (T1DM) occurs in genetically susceptible individuals due to certain environmental triggers causing destruction of insulin secreting beta cells." (PMID 37381634, 2024). "Here we examined the association of diabetes, glycemic control, and requirement for insulin medication with surgical outcomes at 1-month." (PMID 39636335, 2024). "Diabetes is caused when the body is unable to regulate blood sugar properly either due to impaired insulin secretion or sensitivity." (PMID 38540730, 2024). "Various studies have investigated diabetes-related out-of-pocket expenses (OoPEs) for particular products or focused on insulin rationing associated with cost in one clinic or region." (PMID 38711747, 2024). "Diabetes mellitus (DM) is a chronic metabolic disorder recognized by persistently elevated blood glucose levels, commonly due to defects in insulin secretion, function, or absorption mechanisms." (PMID 39355278, 2024).
diabetes (continued). "Both types of diabetes are associated with central changes in the insulin/PI3K/Akt pathway that alter the phosphorylation of glycogen synthase kinase-3β (GSK3β) to promote excess phosphorylation of the microtubule-associated protein tau." (PMID 38416718, 2024). "Reduced levels of zinc can impair the pancreas’s ability to synthesize and secrete insulin and diminish the uptake of glucose by peripheral cells, leading to the development of insulin resistance, a hallmark of diabetes mellitus." (PMID 39195249, 2024). "All comorbidities, with the exception of insulin-requiring diabetes mellitus, were significantly associated with MACE in the multivariable analysis." (PMID 38987835, 2024). "These health outcomes include fat gain, compromised insulin functioning, or increased risk of cardiovascular disease or diabetes." (PMID 39480749, 2024). "In contrast, longer diabetes duration, insulin therapy, and hypoglycemia were linked to lower odds of high adherence (all p < 0.05)." (PMID 39469399, 2024). "Patients with diabetes requiring insulin are at high risk of severe diabetes-related complications during and immediately following concurrent chemoradiation (CCRT)." (PMID 38392055, 2024). "Diabetes is defined by elevated blood glucose levels caused by deficient insulin production or ineffective insulin, and these raised blood glucose levels can damage many organs (such as the eyes and kidneys) by affecting the nervous and circulatory systems." (PMID 39770980, 2024). "Male sex, higher Wagner grades, and high HbA1c in both diabetes types and insulin use in T2D were associated with increased hazard ratios for amputations." (PMID 38403299, 2024). "Insulin gene mutations affect the structure of insulin and are considered a leading cause of neonatal diabetes and permanent neonatal diabetes mellitus PNDM." (PMID 38673052, 2024). "Plant metabolites can modulate various pathways implicated in diabetes pathogenesis, including insulin secretion, glucose production inhibition, and reduction of oxidative stress and inflammation." (PMID 39204124, 2024). "Very often start of insulin therapy in type 2 diabetes mellitus (T2DM) is associated with weight gain and a significant increase of hypoglycemia’s risk." (PMID 38433545, 2024). "A steadily expanding body of evidence has allowed insulin glargine to address and alleviate the commonly held concerns linked to the utilization of basal insulin for managing diabetes." (PMID 38910730, 2024). "Diabetes, on the other hand, characterized by high glucose levels and decreased insulin sensitivity, is another metabolic disorder linked to oxidative stress." (PMID 39204080, 2024). "It is necessary to rethink the disease concept and diagnostic criteria for what we currently call “diabetes mellitus” to include various disorders caused by insufficient or excessive insulin action in addition to abnormal glucose metabolism." (PMID 39513056, 2024). "Diabetes mellitus (DM) is caused by the dysfunction or loss of insulin-producing pancreatic β-cells." (PMID 38916841, 2024). "MODY, the most common type of monogenic diabetes, is caused by a single-gene mutation resulting in impaired β-cell function and decreased insulin secretion." (PMID 38472622, 2024). "Adiponectin and PPAR-γ associated with obesity and diabetes have a directeffect on lipid metabolism, insulin sensitivity, and glucose-energy metabolism." (PMID 38655997, 2024). "Insufficient serum insulin secretion constitutes a significant pathogenic factor in the development of diabetes mellitus." (PMID 39456785, 2024). "Individuals with diabetes who have normal blood pressure tend to exhibit reduced insulin secretion, resulting in a lower risk of hypoglycemia." (PMID 38256662, 2024). "Traditional dried fruits (i.e., those without added sugar), such as grapes, have been shown to reduce the risk of diabetes, likely due to the modulation of insulin resistance status by grape polyphenol extracts." (PMID 39119465, 2024).
diabetes (continued). "In women, we found a higher prevalence of hypertension, obesity, diabetes mellitus, and insulin use, probably associated with the metabolic syndrome." (PMID 39240799, 2024). "Diabetes mellitus (DM), caused primarily by defects in the secretion or action of insulin, is a metabolic disease characterized by hyperglycemia and involves multiple pathogenic processes." (PMID 38987672, 2024). "Diabetes is caused by both excessive insulin resistance and by the body’s inability to produce enough insulin to compensate for the insulin resistance." (PMID 39050622, 2024). "Amylin (islet amyloid polypeptide), commonly known as a diabetes-associated peptide, is secreted in DM patients’ islets of Langerhans in a 1:100 ratio with insulin." (PMID 39493778, 2024). "Of these, type 2 diabetes mellitus (T2DM), which represents more than 90% of people with diabetes, is caused by the decrease in insulin sensitivity or insufficient insulin to overcome insulin resistance (IR)." (PMID 38429305, 2024). "The present study showed decreased insulin sensitivity during the metabolic progression toward diabetes and was associated with a decrease in amylase in pre‐diabetic phase." (PMID 38955666, 2024). "The American Diabetes Association recommends the early initiation of Insulin, whereas commonly gliptins and SGLT-2 inhibitors are considered second-line treatment options." (PMID 39570934, 2024). "Initially, senescence was linked to diabetes in the pancreas, where p16INK4a expression associated with increased insulin secretion." (PMID 37731189, 2024). "During obesity, glucose tolerance is impaired, leading to reduced insulin sensitivity and a higher risk of diabetes." (PMID 39771046, 2024). "It was asserted that the increased level of ALT is related to high serum glucose, low insulin sensitivity, and diabetes risk." (PMID 38678284, 2024). "Regarding self-care, patients with a longer history of diabetes, especially those using insulin, appear most at risk of worsening self-care habits." (PMID 39420900, 2024). "Chromium picolinate is a common dietary supplement, with Cr3+ enhancing insulin activity and reducing the risk of diabetes." (PMID 39135557, 2024). "Subgroup analyses revealed that prolonged diabetes treatment and insulin use were associated with higher fracture risk and worse physical performance while bone characteristics were better." (PMID 39106069, 2024). "Key objectives in diabetes management include achieving glycemic control, understanding insulin regulation, and preventing associated complications." (PMID 38807798, 2024). "Heart, liver, and plasma levels of very-long-chain C24 ceramides are found to be reduced in obesity and diabetes, and their replacement is seemingly metabolically beneficial, increasing weight loss, insulin sensitivity, glucose tolerance, and FFA oxidation." (PMID 39408263, 2024). "Diabetes mellitus (DM) is a metabolic disease characterized by hyperglycemia caused by abnormalities in insulin secretion and/or action." (PMID 38474441, 2024). "Risk factors of hypoglycemia, in addition to the use of insulin, include advancing age, duration of diabetes, kidney disease, alcohol use, malnutrition, prior history of hypoglycemia and presence of impaired awareness of hypoglycemia (IAH)." (PMID 38323079, 2024). "This group of drugs is already known in the treatment of Type 2 Diabetes Mellitus, a condition that can often be associated with obesity, since its pathophysiology involves increased insulin resistance." (PMID 38664450, 2024). "Diabetes mellitus is a metabolic disorder caused by defective glucose tolerance resulting from impaired insulin secretion (type 1 diabetes), defective insulin action (type 2 diabetes), or both." (PMID 38880916, 2024). "Insulin is associated with inflammation reduction, revascularization and wound healing, thereby acting as a protective factor against diabetes-related complications and amputations, in concordance with the topical data." (PMID 38439010, 2024).